IFNAR1 (interferon alpha and beta receptor subunit 1)
Diseases named in the same sentence as IFNAR1 in open-access papers (continued):
Sharing a sentence is not in itself a finding about the gene and the disease.
tumor (continued). "In vitro, IFNAR1 KO and STAT2 KO tumor cells proliferated at similar rates." (PMID 41440237, 2025). "Upon CV-1 treatment, CD80 expression was significantly upregulated in DCs isolated from WT MC38 tumor-bearing mice, but not from IFNAR1 KO MC38 tumor-bearing mice." (PMID 38982116, 2024). "When the tumor infiltrating CD8+ T cells were detected, we found that CV-1 injection into WT tumors increased the percentage of CD8+ T cells among total cells in both injected WT and distant IFNAR1 KO tumors." (PMID 38982116, 2024). "Importantly, tumor control by radiation therapy combined with Enpp1 inhibition is dependent on STING and IFNAR1 expression in host cells, demonstrating that response functions via host sensing of cGAMP." (PMID 39622844, 2024). "This activity is dependent on STING and IFNAR1 expression in non-cancer cells, and tumor destruction by CD8 T cells." (PMID 39622844, 2024). "While pDC depletion alone did not have a big impact on tumor growth, IFNAR1 blockade did have an effect and combination pDC depletion and IFNAR1 blockade had the greatest impact." (PMID 37917174, 2024). "Furthermore, the antitumor effects of KDM3A ablation were weakened by anti‐IFNAR1 antibody treatment, suggesting that KDM3A ablation suppressed tumor growth and enhanced antitumor immunity in a type I IFN dependent manner." (PMID 39031630, 2024). "To clarify the role of the cGAS-STING-NF-κB/IFNβ signaling pathway in the anti-tumor response to zebularine, we treated Cgas-/-, Sting-/-, and sh-Rela/p65 B16F10 tumors implanted into wild-type mice, and sh-Ifnar1 B16F10 tumors implanted into IFNAR1-/- mice." (PMID 38755254, 2024). "Under cisplatin treatment, intraperitoneal injection of IFNAR1 neutralizing antibody led to larger but not statistically different tumor volumes." (PMID 37670034, 2023). "Although we have not studied the role of type III IFN in Cdk4−/− and Cdk6−/− tumor growth, we have transplanted Cdk4−/− and Cdk6−/− cancer cells into Ifnar1−/− mice." (PMID 37833461, 2023). "Indeed, knockout or blockade of IFNAR1 was sufficient to block the enhancement of antigen presentation by BCL2 inhibition in de-iniDCs in vitro, as well as their tumor growth controlling activity in vivo." (PMID 37623817, 2023). "In agreement with this, IFNAR1-independent activation of downstream IFN signaling using IFN-λ improved the immunostimulatory capacity of neutrophils in TDLNs and contributed to the suppression of tumor growth." (PMID 35833131, 2022). "Regarding radiotherapy, type I IFN production by myeloid cells and IFN detection by tumor cells after radiotherapy was essential to eradicate the tumor in a mouse melanoma model, as mice lacking IFNAR1 were unresponsive to IFNβ." (PMID 35251003, 2022). "IFNAR1-independent rescue of type I IFN signaling, using IFN-λ, improves the immunostimulatory capacity of neutrophils in TDLNs and contributes to the suppression of tumor growth." (PMID 35833131, 2022). "Experiments in mouse models have shown that IFNAR1 expression on tumor cells and not host cells is required for the satisfactory efficacy of anthracycline-based therapy." (PMID 35292881, 2022). "IFN receptors (IFNAR) are a class of heterodimers located on the cell membrane and consist of two subunits, IFNAR1 and IFNAR2, and widely distributed, including monocytes, macrophages, B cells, T cells, epithelial cells, endothelial cells, and tumor cells." (PMID 36741390, 2022). "Of note, we observed tumor growth stasis when circulating and tumor cell infiltrating CD8 T cells were immunodepleted, that is, the block in CPA antitumor activity was less complete than with anti-IFNAR1 antibody." (PMID 36187936, 2022).
tumor (continued). "However, Ifnar1 levels in tumor tissues were increased in VPS Tg mice, indicating that VPS9D1-AS1 OE promoting Ifnar1 expression in tumor cells enhanced tumor growth." (PMID 36458816, 2022). "We used an inhibitory IFNAR1 antibody to determine the functional role of type-I IFN signaling and the impact of the transient, downstream induction of ISGs on CPA-induced immune cell recruitment and tumor regression." (PMID 36187936, 2022). "We observed that tumor injection led to a significant downregulation of neutrophil/T-cell interactions in TDLNs of Ifnar1-/- mice, but not in WT mice." (PMID 35833131, 2022). "First, while essential roles of host IFNs signaling in dictating RT have been established, the actual role of tumor expression of IFNAR1 and IFNGR1 may depend on the dose/fraction of RT used and the specific tumor types." (PMID 34830176, 2021). "On d11 and d15 after tumor inoculation, DMXAA treatment also significantly reduced the bone destruction score without changing overall body weight in WT mice, but this effect was abolished in Ifnar1−/− mice." (PMID 34315904, 2021). "Two early studies showed that the IFNAR1 expression in DC (but not tumor cells) plays a dominant role in orchestrating the immunological effects of RT." (PMID 34830176, 2021). "We found that downregulation of IFNAR1 on MDSC was not restricted to the tumor site, it was observed in PB of cancer patients and in spleens of TB mice." (PMID 33741967, 2021). "IFNAR1 is highly expressed in HNSCC patients, where it promotes the expression of programmed death-ligand 1 (PDL1) and programmed cell death protein 1 (PD1) in tumor cells." (PMID 33506058, 2021). "PMN or Mon from tumor-free Ifnar1 KO mice indeed lacked IFNAR1 and yet did not display suppressive activity." (PMID 33741967, 2021). "NK depletion did not have evident effects on Ifnar1-KO tumors after IR, though there was a minor but not significant reduction of tumor response in WT MC38 tumors." (PMID 31483286, 2019). "Consistent with our hypothesis, the therapeutic effect of IFN-α4 was markedly reduced in IFNAR1−/− mice, implying that JAK–STAT signaling in tumor and non-tumor cells is important for the anti-tumor effects of IFN-α4." (PMID 30837996, 2019). "In contrast, positive correlation between IFNAR1 and PDL1 expression was observed in the 108 HNSCC patients (r = 0.425, P < 0.010), and a frequent PDL1 gene amplification was also detected in several HNSCC subtype tumours from TCGA database." (PMID 30555157, 2019). "Abrogation of Ifnar1 in murine cancer cells resulted in an enhanced antitumor response after IR dependent on CD8+ T cells, which generally did not lead to increased numbers, augmented cytotoxic markers, or reduced exhaustion of tumor-infiltrating CD8+ T cells." (PMID 31483286, 2019). "While the Gcsf pathway is upregulated in tumor-bearing animals, steady state Gcsf expression is rather low and not significantly altered between Ifnar1-/- and WT mice." (PMID 31717318, 2019). "The normal tissue had lower IFNAR1 levels than the tumor tissue in the all subject group (p value 0.02) but not in the subgroup of adenocarcinoma or SCC." (PMID 30305853, 2018). "In humans, CRC tumor specimens show elevated mRNA expression of TLR9, IFNAR1, and IL-6, indicating that IFN-I-signaling components and effectors may be good predictors for overall survival." (PMID 28428788, 2017). "Even if pDCS are indeed able to express alpha IFNs without previous stimulation, the comparable elevated tumor growth in Ifnb1−/− and Ifnar1−/− mice demonstrates its irrelevance." (PMID 28066438, 2016). "IFNAR1 and IFNAR2 mRNAs were detected in tumor and non-tumor kidney specimens." (PMID 17697365, 2007). "Together, these observations suggest that the tumor-promoting effects of STAT2 may operate in a tumor-cell intrinsic manner, rather than being driven by differences in IFNAR1-dependent immune signaling." (PMID 41440237, 2025).
tumor (continued). "In this study, we determined that IFNβ upregulates PD-1 expression and knocks out IFNAR1-suppressed PD-1 expression in myeloid cells, revealing that PD-1 expression is regulated by IFN-I/IFNβ at least in part through an autocrine mechanism in myeloid cells in vitro and in tumor-bearing mice in vivo." (PMID 38995014, 2024). "To mimic IFN conditions in the tumor microenvironment (TME), we added IFNγ exogenously in SCC cells since (i) IFNγ pathway is the most significant pathway negatively regulated by TP63, (ii) IFNγ receptors (IFNGR1, IFNGR2) have higher expression than IFNα receptors (IFNAR1, IFNAR2) in SCC cells." (PMID 38509096, 2024). "YTHDF1 expression in BMDCs from Ifnar1-KO mice was not increased by irradiated tumor cells." (PMID 39325547, 2024). "Both endogenous type I IFNs, which are derived from immune and tumor cells, and exogenous type I IFNs, which are produced by recombinant technology, trigger signaling cascades by interacting with their cognate transmembrane receptor, the IFN-α/β receptor 1 (IFNAR1)–IFNAR2 heterodimer." (PMID 35292881, 2022). "Notwithstanding these discrepant findings of the role of IFN-I signaling in ICB resistance between these two studies, both indicated that deletion of IFNAR1 in tumor cells may not mediate primary resistance to ICBs." (PMID 34830176, 2021). "However, since the downregulation of IFNAR1 was markedly stronger in tumors than in spleens, we asked whether anything could further downregulate IFNAR1 in MDSC in the tumor site." (PMID 33741967, 2021). "Consistent with this, IFNAR1 must be expressed by hematopoietic cells (including DCs) but not cancer cells to drive anti-tumor responses elicited by RT, establishing a pivotal role of the cGAS–STING–IFN-I–IFNAR1 axis in DCs in dictating therapeutic effects of RT." (PMID 34830176, 2021). "Mmp2 overexpression in tumor cells is therefore likely to impact other pathways beyond Tlr2/4 signaling that contribute to tumor growth — e.g., degradation of ECM proteins to modify the TME architecture or degradation of IFNAR1 in immune cells (APCs or other cell types) as we previously showed." (PMID 34032639, 2021). "For IFNAR1−/− tumour challenge, grafting rate was 100% with 6/9 tumours growing with similar kinetics as in naïve mice, indicating only a partial and non-robust immunological anti-tumour memory response." (PMID 31530903, 2019). "Therefore, the poor prognosis of HNSCC patients with high IFNAR1 expression may be attributed to the strong immunosuppressive status (i.e., low CD8+ T and CD56+ NK expression, high PDL1 expression) of the tumour microenvironment." (PMID 30555157, 2019). "Serpinb9 restoration did not affect Ifnar1-KO MC38 or B16F10 tumor growth without treatment." (PMID 31483286, 2019). "Therefore, in this study, we evaluated the anti-tumour activity of IFN-α and IFN-β in 11 human pancreatic adenocarcinoma cell lines and assessed the correlation between the responsiveness to type-I IFNs and the expression of IFNAR-1 and IFNAR-2c receptors." (PMID 24460759, 2014). "Importantly, the therapeutic efficacy of Mn‐N/C against tumor growth was absent in Ifnar1−/− mice." (PMID 38308189, 2024). "Similar to NK cells derived from IFNAR1-deficient mice, NK cells isolated from mice lacking type I IFN signaling only at the mature NK cell stage (Ifnar1f/f Ncr1-iCre mice) display a substantial defect in cytolytic capacity against hematopoietic tumor cell lines (YAC-1, RMA-S) in vitro." (PMID 28408907, 2017). "Furthermore, mice lacking IFNAR1 in DC are unable to reject highly immunogenic tumor cells." (PMID 23472200, 2013). "In contrast, IFNAR1 KO MC38 tumors were resistant to CV-1 treatment and tumor-bearing mice showed no benefit of survival." (PMID 38982116, 2024). "This was shown by inhibiting the interferon-1 pathway by blocking interferon-α/β receptor-1 (IFNAR-1) with an antibody during CPA treatment, which greatly inhibited immune cell infiltration, leading to a lack of tumor regression." (PMID 35393476, 2022).
tumor (continued). "We therefore reasoned that CAR T cells generated from donor mice which do not express the type I IFN receptor (IFNAR1) would be protected from the deleterious effects induced by VSVmIFNβ, regardless of the level of type IFN in the tumor." (PMID 32581235, 2020). "While CAR expression was enhanced on WT CD8 T cells cocultured with infected tumor cells in an MOI dependent manner, we observed no change in the surface expression of the CAR on the IFNAR1 KO CD8 T cells." (PMID 32581235, 2020). "The magnitude of the CAR T cell loss was proportional to the concentration of type I IFN in the tumor, and CAR T cells which did not express the IFNAR1 were largely refractory to virus-induced attrition in the setting of lymphodepletion or NK cell depletion." (PMID 32581235, 2020). "The absolute level of mRNA expression for IFNAR1 and IFNAR2 in the tumor and non-tumor tissues did not correlate with the malignant and the metastatic profiles of the RCC tumors." (PMID 17697365, 2007). "The absolute level of IFNAR1 and IFNAR2 mRNAs in tumor and non-tumor tissues did not correlate with the malignant and metastatic profiles." (PMID 17697365, 2007). "However, only the growth of IFNAR1-depleted GL-261 tumors and not that of SMA-560 tumors was delayed in vivo upon orthotopic tumor cell implantation into syngeneic mice." (PMID 36571986, 2023). "Collectively, these studies establish a pivotal role of IFNAR1 expression (either on immune cells or tumor cells) in governing IO efficacy, but direct evidence of IFN-Is in this process is lacking, given that tumor expression of IFNAR1 can be regulated by ligand-independent mechanisms (e.g., MAPK)." (PMID 34830176, 2021). "To test whether these effects were dependent on host-intrinsic STING and Ifnar1, we measured local tumor burden using thigh circumference at d17 in STINGgt/gt and Ifnar1−/− mice and found that this protective effect was abolished in mice lacking either STING or Ifnar1." (PMID 34315904, 2021).
cancer (70 papers, 2008 to 2025). A tumor composed of atypical neoplastic, often pleomorphic cells that invade other tissues. "To identify key components involved in MHC-I upregulation via CDK12/13 antagonism, we knocked out Cgas, Sting1 (encoding STING), Ifnar1 (encoding IFNAR1), or Rela (encoding p65) in cancer cell lines." (PMID 40955658, 2025). "We demonstrated that reserpine, a discontinued blood pressure medication, suppressed EV incorporation and prevented cancer cell EV-mediated cancer progression by suppressing the loss of IFNAR1 and CH25H." (PMID 38405101, 2024). "For example, IFN alpha receptor (IFNAR)–1 knockout (KO) in mouse cancer cells provoked pronounced immune responses after ionizing radiation, and the cancer cells were more susceptible to CD8+ T cell-mediated killing." (PMID 36458816, 2022). "To search for candidate genes underlying the enhanced susceptibility of Ifnar1-KO cancer cells, we generated a panel of 12 plausible candidates for an initial survey." (PMID 31483286, 2019). "Furthermore, IFNAR1 downregulation in cancer-associated stromal cells was observed in colon and pancreatic cancers." (PMID 34381458, 2021). "Serpinb9 is the key mediator of enhanced susceptibility of Ifnar1-KO cancer cells." (PMID 31483286, 2019). "Thus, in vivo as in vitro, Ifnar1-KO cancer cells showed greater susceptibility to CD8+ T cell–mediated killing than WT cells." (PMID 31483286, 2019). "Thus, overexpression of Serpinb9 in Ifnar1-KO cancer cells reversed their augmented susceptibility to CD8+ T cell–mediated killing." (PMID 31483286, 2019). "Since we found little alteration in CD8+ T cell numbers or functional markers in Ifnar1-KO compared with WT tumors, we next asked whether Ifnar1-KO cancer cells were more susceptible to CD8+ T cells." (PMID 31483286, 2019). "Ifnar1-KO cancer cells are more susceptible to CD8+ T cell–mediated killing." (PMID 31483286, 2019). "For example, mice with conditional deletion of the type I IFN receptor (IFNAR1) in intestinal epithelial cells had an altered gut microbiota composition, which promoted epithelial hyperproliferation and experimental colitis-associated cancer." (PMID 28713378, 2017). "Since irradiation of these cancer cells leads to cell cycle arrest and lack of viability, but only low levels of apoptosis, and since T cell killing is driven by apoptosis, we used apoptosis as an endpoint to ask whether irradiated Ifnar1-KO cancer cells were also more susceptible to apoptosis." (PMID 31483286, 2019). "As anticipated, knockout (KO) of Cgas, Sting1, or Ifnar1 abolished MHC-I induction by CDK12/13 antagonism in various cancer models." (PMID 40955658, 2025). "The DEGs down-regulated in IFNAR1 KO MDBK cells infected with BVDV were mainly involved in cancer, Hippo, TGF-β, and mTOR pathways." (PMID 39100665, 2024). "Authors in cancer studies referred to the tumour-promoting effects of IFN-1 as protumorigenic interferon alpha receptor 1 (IFNAR1)." (PMID 39070493, 2024). "In the same study, a cancer-specific IFN-I receptor (IFNAR1) provided a stemness state and the release of exosomes derived from CSCs carrying receptor ligands associated with immune checkpoint function." (PMID 35982868, 2022). "This study also showed that IFNAR1 expression in cancer cells is important for the activity of anthracyclines, as administration of an IFNAR1 neutralizing antibody abolished the therapeutic activity of the drugs." (PMID 35251003, 2022). "These include: (i) degradation of IFNAR1 in cancer and immune cells through ubiquitination driven by the phosphorylation on serine residues." (PMID 34571733, 2021). "Colorectal samples from cancer patients display a reduced expression of IFN receptor 1 (IFNAR1) as compared to healthy samples." (PMID 34680504, 2021). "In contrast, cancer patients’ PMN-MDSC demonstrated markedly lower expression of IFNAR1 than PMN from healthy donors." (PMID 33741967, 2021).